IL6 (interleukin 6)
Diseases named in the same sentence as IL6 in open-access papers (continued):
Sharing a sentence is not in itself a finding about the gene and the disease.
COVID-19 (continued). "In our investigation, we discerned that the levels of S1RBD IgG, along with cytokines IL-6, IL-6R, TNF-α, IL-10, and IL-1β, were markedly elevated in the individuals who received two or three doses of the mRNA COVID-19 vaccine compared to those who received a single dose." (PMID 38932387, 2024). "Recent research highlights the importance of IL-6 trans-signaling, rather than the classic signaling, in driving the hyperinflammatory responses seen in severe COVID-19." (PMID 39518964, 2024). "Indeed, recent evidence suggests that elevated IL-6 and TNF-α levels can predict disease severity and survival in patients with COVID-19." (PMID 39113083, 2024). "A distinct immune response is noted between COVID-19 and MIS-C, characterized by a persistent elevation in pro-inflammatory cytokines such as IL-1β, IL-2, IL-6, IFN-α, IL-10, IL-17, granulocyte-macrophage colony-stimulating factor (GM-CSF), and high-mobility group box 1 (HMGB1) among MIS-C patients." (PMID 39931580, 2024). "Besides supporting existing knowledge on especially IL-1ra, IL-6, IL-8, and MCP-1 in relation to COVID-19, our study has provided additional insight into lesser investigated chemokines associated with adverse outcomes in COVID-19 patients." (PMID 38985797, 2024). "Likewise, there was an increase in IL-6 and CRP in COVID-19 patients in comparison with HSs (p ≤ 0.001), and treatment with Vit E decreased their levels (p ≤ 0.001)." (PMID 39057070, 2024). "COVID-19 exhibited a distinct immunological profile characterized by increased levels of Th1 (IL-12 and IFN-γ) and Th2 (IL-4, IL-5, IL-10, and IL-13) cytokines, along with IL-1β and IL-6, among other markers." (PMID 39408907, 2024). "Additionally, studies have demonstrated that severe COVID-19 cases may trigger a cytokine storm, characterized by an overactive T lymphocyte immune response and elevated levels of pro-inflammatory cytokines, such as interleukin 6 (IL-6) and tumor necrosis factor-alpha (TNF-α)." (PMID 40735669, 2024). "Their study revealed that the consumption of NBS powder over a duration of 4 weeks yielded a significant influence on the levels of proinflammatory cytokines, particularly interleukin-6 (IL-6) and tumor necrosis factor α (TNF-α), in individuals afflicted with COVID-19." (PMID 38522056, 2024). "Several different therapies, including steroids, IL-6-inhibitors, JAK-inhibitors, IL-1 receptor antagonists, and TNF-α inhibitors, have been reported to be beneficial in the treatment of selected groups with COVID-19." (PMID 38985797, 2024). "Another pathological pathway is represented by the dysregulation of the immune system and, because of the activation of endothelial cells and macrophages, a hyperinflammatory phase appears during COVID-19 with the enormous release of TNF-α, IL-1, IL-2, IL-6, IL-8, and chemokines." (PMID 38999316, 2024). "In additional experiments, we also investigated the potential action of the nutraceutical formula on other inflammatory genes with a role in innate immunity (i.e., C3, IL-1β, IL-6, CXCL10 and CXCL12) whose modulation have been reported in COVID-19 pathogenesis and progression." (PMID 38886736, 2024). "This means that among biomarkers, elevated levels of CRP, serum ferritin, and IL-6 were significant in patients with COVID-19 and renal injury compared to patients without renal involvement." (PMID 38975470, 2024). "The serum levels of interleukin (IL)-6 and sCD25 were elevated in acute COVID-19; this was not influenced by the presence of immunosuppression." (PMID 38791279, 2024). "Melatonin could resolve hyper-inflammatory conditions in COVID-19 and PASC by down-regulating proinflammatory cytokines (i.e., TNF-α, IL-1β, IL-6, and IL-8) and increasing anti-inflammatory cytokines such as IL-10660,661." (PMID 38555403, 2024). "Although no COVID-19 was detected in conjunctival secretions, increased IL-6 was noted to be increased." (PMID 38576676, 2024).
COVID-19 (continued). "According to another meta-analysis comprising nine studies, patients with severe COVID-19 had a significantly higher mean concentration of IL-6 was than those with non-severe symptoms (mean difference of 38.6ng/L)." (PMID 38355623, 2024). "However, this does not negate the importance of other haematological markers that have shown their value in predicting COVID-19-related mortality, such as C-reactive protein (CRP) and interleukin (IL)-6." (PMID 38674248, 2024). "Given that IL-6 levels in the serum are predictors of COVID-19 severity, it is not surprising that tocilizumab is used to treat COVID-19 patients." (PMID 39835136, 2024). "In addition to the upregulation of AMPs in the nasopharynx during SARS-CoV-2 infection, we observed increased gene expression profiles of IFN-γ, TNF-ɑ, and IL-6 in COVID-19 patients, which was further confirmed at the protein level for IFN-γ and IL-6." (PMID 39339947, 2024). "Indeed, multiple studies have reported increased levels of inflammatory or coagulation markers such as IL-6, CRP, C-reactive proteins, procalcitonin, ferritin and D-dimers in more severe forms of COVID-19 compared to less severe ones." (PMID 38814977, 2024). "Biomarkers for multisystem inflammation include elevated tissue damage markers, inflammatory markers, proinflammatory cytokines including IL-6, IL-1, CXCL10 and IL-10, and lymphopenia; while viral RNA detected in the blood remains one of the most accurate early indicators of COVID-19 mortality." (PMID 39737903, 2024). "We propose that age, severity of illness, comorbidities, IL-6, and NLR could serve as effective indicators for predicting RP within two weeks in COVID-19-recovered patients." (PMID 37702601, 2024). "Serum levels of SAA, hsCRP and IL-6 were all raised in two COVID-19-infected groups (SAA < 0.01, hsCRP < 0.01, IL-6 < 0.05), but PCT, ALT, LDH and HBDH levels were only elevated in ≥ 10 days COVID-19 group (PCT = 0.0478, ALT = 0.0022, LDH = 0.0313, HBDH = 0.0077)." (PMID 38902401, 2024). "A meta-analysis showed almost 3-fold higher serum IL-6 in patients with complicated COVID-19 compared to those with non-complicated disease." (PMID 38791005, 2024). "Pro-inflammatory cytokines such as interleukins IL-2, IL-6, tumor necrosis factor-alpha (TNF-α), interferon-gamma (IFN-γ), and many other molecules, including chemokines, play a significant role in the pathophysiology of COVID-19." (PMID 38707035, 2024). "Importantly, PRL has been shown to regulate the expression of cytokines such as IL-1β, IL-6, and TNF-α, which are key players in the inflammatory response observed in severe COVID-19 cases." (PMID 39595974, 2024). "Although IL-10 and IL-6 were not correlated within the group of patients with severe COVID-19, they were directly proportional in deceased and non-severe groups." (PMID 39633683, 2024). "Also, increased levels of the endothelial tPA receptor, annexin A2, correlated with inflammatory markers (i.e., IL-1β, IL-6, and TNF-α) and COVID-19 magnitude." (PMID 38378550, 2024). "Despite these limitations, our study has some obvious strengths, especially using the hypothesis-driven approach, we provide insight into the specific roles of IL6 and IL6R in COVID-19 progression, providing targeted insights into this crucial pathway." (PMID 39040605, 2024). "Similarly, clinical biomarkers like IL-6, CRP, LDH, and D-Di have been identified as predictors of disease progression and treatment outcomes in COVID-19." (PMID 39712749, 2024). "As a result of direct or indirect antagonism of IL-6 via the JAK-STAT pathway, it has been shown to improve the prognosis of hospitalized COVID-19 patients with hypoxia and systemic inflammation, IL-6 may be a biomarker closely related to treatment." (PMID 38638307, 2024). "Elevation of both IL-6 and LRG1 in patients with COVID-19 suggests that circulating pro-inflammatory IL-6 may induce systemic and local upregulation of angiopathic LRG1 in the pulmonary microvasculature." (PMID 38745756, 2024).
COVID-19 (continued). "On the other hand, studies have shown that IL-6 and TNF-α levels increase in COVID-19 patients." (PMID 38524183, 2024). "Although a direct correlation between viral load and IL-6 production is not well established, COVID-19 patients exhibit a direct or indirect relationship with the viral infection." (PMID 39458339, 2024). "We performed a cross-sectional study aimed to investigate the changes in circulating levels of arachidonic acid, interleukin 6 (IL-6), and C-reactive protein (CRP) in patients with FluA, RSV, or COVID-19, and to analyze the potential of these parameters as diagnosis or prognosis biomarkers." (PMID 39066228, 2024). "Another study involved 91 patients with COVID-19 infection, out of whom 14 (19.72%) were diagnosed with T2DM and exhibited elevated levels of IL-6 compared to non-DM patients with COVID-19." (PMID 38675414, 2024). "Lastly, at the time of the study, the SOC for treatment of severe COVID-19 did not yet include interleukin-6 (IL-6) inhibitors such as tocilizumab, and thus baseline use of this treatment in our study was low (9–11% of patients)." (PMID 39522090, 2024). "These insights contribute to a more profound understanding of the inflammatory cascade in COVID-19 and reinforce the potential of NLR and IL-6 as biomarkers for guiding therapeutic strategies, particularly in the high-stakes decision-making process around intubation and ventilatory support." (PMID 39203987, 2024). "Similarly, all common infection indicators at admission (including serum WBC count, PCT, CRP, IL-6, D-Dimer, and LDH level) in COVID-19 subgroup with secondary infection were great higher than that of patients without bacterial infection (p < 0.05)." (PMID 38246947, 2024). "Another important cytokine is IL-6, a molecule which is profoundly raised in severe COVID-19, but also considerably raised in non-severe COVID-19." (PMID 38257799, 2024). "As reported in COVID-19 patients, both sgp130Fc and JAK inhibitors ruxolitinib can block IL-6 trans-signaling with decreased phosphorylation of JAK1 and STAT1/3, resulting in the inhibition of proinflammatory factors production and the alleviation of liver injury." (PMID 38890694, 2024). "Our research also finds that IL-6 and CRP is significantly increased, suggesting that inflammation may be one of the mechanisms contributing to myocardial harm in cases of COVID-19." (PMID 38706946, 2024). "The median IL-6 concentration in critical COVID-19 was 55 pg/mL (Q1 = 31 pg/mL, Q3 = 120.88 pg/mL), while in non-critical COVID-19 the median concentration was 27.75 pg/mL (Q1 = 17 pg/mL, Q3 = 55.38 pg/mL)." (PMID 39518552, 2024). "Also, the CSF IL-6, IL-8, IL-15, and monocyte inhibitory protein (MIP)-1β levels were higher in COVID-19 patients with neurological symptoms compared to controls and human immunodeficiency virus (HIV) patients, with evidence of BBB disruption." (PMID 38641847, 2024). "Higher levels of IL-6 and CRP were found in numerous studies as markers of COVID-19 severity." (PMID 38686386, 2024). "Despite the lack of differences observed regarding IL-6 as a biomarker for COVID-19 severity, our data are in agreement with the key role of both inflammatory factors in mediating the acute immune response." (PMID 39061002, 2024). "The severe COVID-19 patients were older, had significantly more comorbidities, and significantly higher neutrophil/lymphocyte ratio, C-reactive protein, and interleukin-6 than the non-severe COVID-19 patients (all p < 0.05)." (PMID 38504259, 2024). "In general, the IL-6 assay run on the full-automated platform by the ECLIA method has great applications in most laboratories for rapid diagnosis and monitoring of the immune response in COVID-19 patients." (PMID 38617587, 2024). "Vit-D, 25-OH vitamin D; DBP, Vitamin D binding protein; PCT, Procalcitonin; TnT, Troponin-t; IL-6, Interleukin-6; 0, COVID-19 negative; 1, COVID-19 positive." (PMID 39139171, 2024).
COVID-19 (continued). "The aim of this study was to investigate whether bioactive adrenomedullin (bio-ADM) and interleukin-6 (IL-6) are related to acute kidney injury (AKI) and severe illness in COVID-19 patients." (PMID 38336628, 2024). "We were limited to using genetic instruments for whole-blood levels of IL-6 traits, given the current lack of large-scale GWASs, and, hence, genetic instruments for IL-6 traits in tissues that are possibly more relevant to COVID-19 (e.g., lung tissue)." (PMID 39062668, 2024). "In this first study of its kind designed to assess the impact of RIC on inflammatory cytokines in participants admitted to hospital with COVID-19, we were unable to detect a significant reduction by RIC in levels of pro-inflammatory cytokines (including IL-1β, IL-6, and TNF-α)." (PMID 36445625, 2024). "No significant IL-6 concentration difference was detected between COVID-19 patients with chronic CVD co-morbidities and healthy controls (adjusted p = 1.000)." (PMID 39518552, 2024). "While vitamin D deficiency appeared to be linked to increased inflammation, as evidenced by elevated IL-6 expression, the lack of significant relationships with other clinical outcomes implies that vitamin D levels may not independently influence patient outcomes in elderly COVID-19 patients." (PMID 39062991, 2024). "The pro-inflammatory cytokines that signal via the JAK-STAT signalling pathway include IL-2, IL-6, IL-8 and TNF-α, all of which are elevated in severe COVID-19, as well as antiviral or anti-inflammatory cytokines such as IFN-γ and IL10, which are also elevated in severe COVID-19." (PMID 39051370, 2024). "A high expression of IL-6 and TNF-α characterizes the cytokine storm in COVID-19." (PMID 39063142, 2024). "In the hyperinflammatory state, such as critical phase of COVID-19 with the acute elevation of tumor necrosis factor (TNF)-α and interleukin (IL)-6, serum concentrations of HDL-C and apoA-I significantly decreased and were negatively correlated with COVID-19 severity." (PMID 38791598, 2024). "IL-6 and TNF-α have been confirmed to be critical cytokines in the pathogenesis of COVID-19, and their levels are correlated with the severity and prognosis of COVID-19." (PMID 39650159, 2024). "The immune inflammation factors, such as IL-6, IL-8, IL-10, CD8+ cell and NK cell, could serve as excellent biomarkers for monitoring or predicting COVID-19 progression therapeutic to COVID-19 patients." (PMID 38173531, 2024). "IL-6 is a proinflammatory cytokine, and high plasma levels of IL-6 serve as a strong predictor for nonsurvival in COVID-19 patients." (PMID 38306481, 2024). "Based on IL-6 concentrations, COVID-19 patients with no co-morbidities were correctly classified in 81.3%, while CVD patients with statin consumption were correctly classified in 43.8% of cases." (PMID 39518552, 2024). "Acute respiratory SARS-CoV-2 infection generates a robust systemic cytokine response in addition to type I and type II interferon responses, and the plasma levels of IFN-α, IFN-γ, IL-1β, IL-6, and TNF-α are significantly increased in human patients with acute COVID-19." (PMID 39062017, 2024). "Also increased urea, enzymes (AST, CK), D-dimers, procalcitonin, ferritin, and IL-6; and decreased GFR, albumin, lymphocytes, and platelets are markers with unfavorable prognosis for COVID-19 in T2D patients during the treatment period." (PMID 38398069, 2024). "Due to missing data on interleukin-6 concentration on hospital admission, it was not possible to calculate the COVID-19 Lab score in our population." (PMID 39436870, 2024). "Furthermore, COVID-19 mRNA-LNP vaccines encompass adjuvants, such as LNPs, which trigger inflammatory cytokines, including interleukin (IL)-1β and IL-6." (PMID 39452475, 2024).
COVID-19 (continued). "For this purpose we relied on the Comparative Toxicogenomic Database (CTD), GeneMANIA, and ToppGene Suite portal and identified a set of five common genes (IL1B, CXCL8, IL6, IL10, TNF) for the six metals and COVID-19, all of which code for pro-inflammatory and anti-inflammatory cytokines." (PMID 38963144, 2024). "The primary objective of this study is to assess the predictive value and diagnostic potential of specific interleukins (IL-10, IL-17A, IL-1β, IL-6), chemokines (CXCL), and monocyte chemoattractant protein (MCP) in predicting severe COVID-19 outcomes and mortality." (PMID 39062105, 2024). "The study reported significantly elevated IL-6 levels in both diabetic and non-diabetic patients with severe COVID-19, reflecting the pathological effects of the virus." (PMID 39518964, 2024). "Among patients enrolled within 7 days of symptom onset, evidence of pro-inflammatory monocyte/macrophage (IL-1Ra, IL-1β, IL-6, CXCL10), NK cell (IL-15), Th1/Th17-pathway (IL-7, IL-15, IL-17F), and endothelial (VEGF-A) activation were apparent in patients with severe COVID-19." (PMID 38368384, 2024). "Furthermore, elevated pro-inflammatory cytokines such as IL-6, IL-1β, and monocyte chemoattractant protein 1 (MCP-1) in COVID-19 patients affect endothelial function and integrity." (PMID 38214889, 2024). "A binary logistic regression model was applied to our data regarding the COVID-19 patients with chronic CVD using statins and COVID-19 patients with no cardiovascular co-morbidities, with statistically significant differences in IL-6, TNFα, and IL-10 concentrations." (PMID 39518552, 2024). "Not only that, the assessed efficiency of serum transglin was not less than COVID-19 severity scores and was a little higher than those in commonly inflammatory cytokines, such as IL-6 and CRP." (PMID 39676863, 2024). "The relationship between the severity of COVID-19, patient outcomes, and the values and dynamics of biomarkers such as leukocytes, neutrophil-to-lymphocyte ratio (NLR), CRP, ASAT, LDH, D-dimers, ferritin, and IL-6 has been demonstrated in numerous studies." (PMID 39767597, 2024). "A cytokine storm, driven by an imbalance of T-cell activation and dysregulated release of interleukin (IL)-6, IL-17, and other cytokines, may contribute to CVD in COVID-19." (PMID 39189008, 2024). "Therefore, our study was aimed to investigate the changes in circulating levels of arachidonic acid, IL-6, and CRP in patients with FluA, RSV, or COVID-19, and to analyze the potential of these parameters as diagnosis of prognosis biomarkers." (PMID 39066228, 2024). "Indeed, significant correlations exist between levels of TNF-α, IL-6, IL-1β, IL-10, IFN-γ, and CCL2 with cognitive and behavioral changes in COVID-19 patients, thus showing generalized neuroinflammation." (PMID 39767737, 2024). "The strengths of our study include that it is the first time to detect decreased NEAT-1 in the serum of COVID-19 patients and the first study to measure serum miR374b-5p in COVID-19 patients and to correlate its level with NEAT-1, IL6, and other laboratory findings." (PMID 39729489, 2024). "At 9–12 weeks after disease onset, participants who had initially severe COVID-19 tended to have significantly higher levels of IP10 and sCD163 and lower levels of IL10, IL6, TNFα, IL17 and IL13 compared to those with mild or moderate disease, when adjusting for other covariates." (PMID 39008486, 2024). "There is research showing that cytokines closely related to cytokine storms (IL-6, TNF-α) and chemokines such as CXCL10 and CCL2 are significantly elevated in COVID-19 patients with diabetes, indicating that these patients are more prone to excessive inflammatory responses post-infection." (PMID 39654886, 2024).